MUC4 (mucin 4, cell surface associated)
Diseases named in the same sentence as MUC4 in open-access papers (continued):
Sharing a sentence is not in itself a finding about the gene and the disease.
melanoma (9 papers, 2001 to 2025). A malignant, usually aggressive tumor composed of atypical, neoplastic melanocytes. "The SMGs identified in our mouse models included well-described melanoma and leukemia oncogenes and tumour suppressors (Muc4, Pten, Grin2a, Dnmt3a, Npm1 and Flt3) reinforcing the WES validation and the subsequent filtering of SMGs." (PMID 39223638, 2024). "It is of note that in these three cases AHNAK2, MUC4, MUC16, and MUC17 mutations were found, which were previously reported to be involved in antitumoral immune mechanisms of melanoma." (PMID 36980598, 2023). "Under optimal conditions 1G8s stained rat MUC4 inducibly expressed in A375 melanoma cells, revealing a uniform cell surface expression pattern in all cells of the field." (PMID 19761616, 2009). "Inducible expression of rat MUC4 in human A375 melanoma cells has been demonstrated to augment primary tumor growth and metastasis in a nude mouse xenograft model." (PMID 19761616, 2009). "Finally, specific examples of subclonality, such as MUC4 PMs in melanoma and SOX2 gains in lung, have been identified." (PMID 25160065, 2014). "Indeed, ectopic overexpression of rat MUC4 in a human melanoma model cell line increased primary tumor growth and metastasis efficiencies when introduced into nude mice." (PMID 19761616, 2009). "Immunohistochemically, the tumor cells were positive for S100 (5/6), cyclin D1 (2/3), SATB2 (2/3), BCOR (2/4), and TLE1 (1/3) while negative for MUC4 (0/6), keratin (0/5), EMA (0/4), desmin (0/6), CD34 (0/6), SMA (0/5), SOX10 (0/5), and pan melanoma (0/2)." (PMID 40705064, 2025). "Immunohistochemically, the tumor cells were positive for S100 (5/6), cyclin D1 (2/3), SATB2 (2/3), BCOR (2/4), and TLE1 (1/3) while negative for MUC4 (0/6), keratin (0/5), EMA (0/4), desmin (0/6), CD34 (0/6), SMA (0/5), SOX10 (0/5), and melanoma cocktail (0/2)." (PMID 40705064, 2025).
prostate carcinoma (9 papers, 2004 to 2021). A carcinoma that arises from epithelial cells of the prostate gland. "Genes such as BUB1B, ANX1A1, F5, HTR4, and MUC4 can be used as biomarkers to assist in the diagnosis and prognosis of prostate cancer." (PMID 34512870, 2021). "Of note was PI3K family members: PIK3C2G, PIK3CA, PIK3CB, PIK3R4, Mucin family members: MUC1, MUC4 and MUC6 and other prostate cancer associated genes such as SMAD4, SOX9 and SPOP7,9,40,41." (PMID 32796921, 2020). "Treatment of prostate cancer cell lines with inhibitor of histone deacetylases and DNA methyl transferases lead to increased expression of MUC4." (PMID 24671186, 2014). "Our study has proven that MUC4 is downregulated in prostate cancer tissues, like other literatures." (PMID 34512870, 2021). "The cell surface membrane-bound mucin protein MUC4 promotes tumorigenicity, aggressive behavior, and poor outcomes in various types of epithelial carcinomas, including pancreatic, breast, colon, ovarian, and prostate cancer." (PMID 27829225, 2017).
bladder cancer (8 papers, 2014 to 2022). "Further studies are warranted to decipher the molecular mechanism and effect of MUC4 loss on development of bladder carcinoma." (PMID 24671186, 2014). "We selected generic exosome markers CD9, CD63, and TSG101, as well as the EDIL-3 and MUC4 for Western blotting analysis of urinary exosome proteins prepared by UC and NanoPoms methods, with the human bladder carcinoma cell line HTB9 as the control." (PMID 35787656, 2022). "This dataset reveals all 10 H4205Q MUC4 mutations occur as 10 G < C; half of which are from KIRC, three from bladder cancer, and two from LUAD." (PMID 28978023, 2017). "Expression of other mucins such MUC2 and MUC6 were associated with a less aggressive behavior of bladder tumours and demonstrated to be useful predictors of better bladder cancer survival while MUC4 demonstrated an opposite role." (PMID 29207682, 2017). "Altered expression and localization pattern of MUC1 have been observed during progression of malignant neoplasms of bladder, however to date there is a dearth of information on the status of MUC4." (PMID 24671186, 2014). "After analyzing the expression of mucins in various bladder pathologies by immunohistochemistry, the expression of MUC1 and MUC4 was analyzed at mRNA and protein levels in different bladder carcinoma cell lines." (PMID 24671186, 2014). "The present study examined the expression of TM mucins MUC1 and MUC4 in bladder tissue microarray, tissue sections and bladder carcinoma cell lines." (PMID 24671186, 2014). "MUC4 expression is increased in bladder cancer vs ANT (GSE13507, p < 0.01)." (PMID 30236127, 2018). "The serum bound strongly to proteins in cell lysates from MUC4+ PDAC cells such as HPAC and HPAF but not to proteins in cell lysates from MUC4− PDAC cells such as PANC-1 or to other MUC4− tumor cells such as T24 bladder carcinoma cells (data not shown)." (PMID 30952968, 2019). "In the present study, we investigated the expression profile of MUC1 and MUC4 in the non-neoplastic bladder urothelium, in various malignant neoplasms of bladder and in bladder carcinoma cell lines." (PMID 24671186, 2014). "No expression of MUC1 and MUC4 was observed in T24 bladder carcinoma cell line." (PMID 24671186, 2014). "Overall, mucin MUC1 and MUC4 analyses in bladder cancer TMA and tissue sections indicated that the expression of MUC1 is increased while that of MUC4 decreased in UC compared to the normal non-neoplastic urothelium." (PMID 24671186, 2014).
chronic pancreatitis (8 papers, 2004 to 2024). A chronic inflammatory process causing damage and fibrosis of the pancreatic parenchyma. "MUC4 has already been linked to PDAC as an aberrantly expressed gene with no detectable expression in normal pancreas or chronic pancreatitis." (PMID 20553613, 2010). "MUC4 is a high molecular weight, type I transmembrane glycoprotein that is overexpressed in PC but absent in normal pancreas and chronic pancreatitis." (PMID 23102107, 2012). "While MUC1, MUC4, and MUC5AC are the most differentially overexpressed mucins in human PDAC, the selective increase of MUC6 expression was identified as a potential biomarker for human chronic pancreatitis when compared to normal pancreas and PDAC in an unbiased screen." (PMID 25803032, 2015).
cholangiocarcinoma (7 papers, 2012 to 2023). A carcinoma that arises from the intrahepatic biliary tree (intrahepatic cholangiocarcinoma) or from the junction, or adjacent to the junction, of the right and left hepatic ducts (hilar cholangiocarcinoma). "For example, MUC4 has been recognized as a prognostic factor of Cholangiocarcinoma (CC) by several studies." (PMID 36081995, 2022). "RiskScore of cholangiocarcinoma patients with 10 genes calculated followed the formula: The RiskScore=0.429*VEGFC -0.434*NFKBIA-0.884*NLRX1+0.54*AKT1+0.629*CSRP1+0.406*EPO+0.833*IL31RA+1.023*LEP+0.341*MUC4+0.363*SEMA4B." (PMID 36817485, 2023). "Among all 10 prognostic specific immune-related genes, 4 genes (AKT1, EPO, MUC4, VEGFC) were considered as important predictors of relapse-free or overall survival and were implicated in immune microenvironment-related pathogenesis of cholangiocarcinoma." (PMID 36817485, 2023). "As to the biliary epithelial cells, MUC4 is not expressed in normal bile duct and gallbladder cells, but is expressed in cholangiocarcinoma cells." (PMID 23101681, 2012).
asthma (6 papers, 2006 to 2023). "In human, it has been reported that MUC5AC expression, measured using real-time RT-PCR, is much higher than both MUC5B and MUC4 in homogenates of endobronchial biopsies from healthy subjects or subjects with asthma." (PMID 17550583, 2007). "While emphasizing the critical role of IL-13 in asthma, this study explored the relevance of IL-4 in regulation a membrane bound mucin, MUC4." (PMID 16551361, 2006). "To determine the effects of IL-31 on the expression of asthma-associated genes, we quantified the expression of genes associated with inflammation (IFNγ, TNF-α, IL-6, and IL-17) and Th2 responses (IL-4, IL-13, ARG1, MUC4, and MUC5AC)." (PMID 38081868, 2023). "In our study, we examined the expression levels of critical members of the mucin family, specifically the secreted mucins MUC5AC and MUC5B, in addition to the membrane-bound mucins (MUC1, MUC4, and MUC2) in lung tissue obtained from the TIMPKO murine asthma model." (PMID 34221020, 2021).
biliary tract cancer (6 papers, 2008 to 2022). "In biliary tract cancer, there is a roughly 1.9-fold increase in MUC4 mRNA levels, and increased MUC4 expression is associated with a decreased survival rate among these patients." (PMID 27829225, 2017). "The diagnostic sensitivity of MUC4 in bile is 27%, and although the sensitivity of combined serum MUC5AC in the diagnosis of biliary tract cancer can be increased to 58%, it is still too low to be used as a diagnostic biomarker for biliary tract cancer." (PMID 36010914, 2022). "MUC5AC is a serum candidate biomarker for the diagnosis of biliary tract cancer, and MUC4 is also an independent factor for the evaluation of iCCA and eCCA." (PMID 36010914, 2022). "This kept consistent with the findings from Matull WR who found that increased expression of MUC4 was highly specific to biliary tract cancers and significantly determined a poorer long-term outcome." (PMID 27305093, 2016). "Furthermore, MUC4 expression predicted a shorter survival length in patients with biliary tract cancers." (PMID 27305093, 2016). "In his study, aberrant expression of MUC4 was found in 37% of the biliary tract cancer specimens and 29% of the primary sclerosing cholangitis bile samples, whereas such expression could be hardly seen in benign biliary tissues." (PMID 27305093, 2016).
COVID-19 (6 papers, 2021 to 2025). A disease caused by infection with severe acute respiratory syndrome coronavirus 2. "Co-localization analysis identified LZTFL1, MUC4, OAS1, HLA-C, SLC22A31, FDX2, and MAPT as genes involved in COVID-19-mediated causation of MM." (PMID 38400850, 2024). "It is interesting to note that MUC21 mRNA expression was only selected as a variable associated with COVID-19 severity, whereas MUC13, MUC4, and MUC6 mRNA expression were uniquely identified as variables indicative for COVID-19 presentation." (PMID 34448730, 2021). "Mucin 4 (MUC4) that is downregulated in the blood of critically ill COVID-19 patients." (PMID 36143338, 2022). "By using the same approach, we also showed that age and mRNA expression of MUC1, MUC2, MUC4, MUC6, MUC13, MUC16, and MUC20 were the most accurate variables associated with the presence of COVID-19 among symptomatic patients (AUCROC = 91.8%; sensitivity: 90.6%; specificity: 93.3%)." (PMID 34448730, 2021). "Interestingly, expression of MUC4 mRNA was significantly lower in the critically ill COVID-19 group compared with the mild patient groups and was significantly increased in the mild non–COVID-19 group compared with healthy controls." (PMID 34448730, 2021). "MUC1, MUC2, MUC4, MUC16, and MUC20 mRNA expression strongly correlated with COVID-19 severity, of which MUC1 and MUC20 mRNA expression also associated significantly with age and MUC16 and MUC20 mRNA expression with sex." (PMID 34448730, 2021). "In large airway tissues, genes related to the mucosal layer (MUC4, MUC5AC, MUC5B) as well as cytokine-mediated signaling pathway genes (CCL20, CXCL1, CXCL6, CXCL6, MMP1) and type I interferon genes (IFIT3, ISG15, STAT1, MX1) were upregulated in COVID-19." (PMID 35233546, 2022).
gastric adenocarcinoma (6 papers, 2008 to 2023). "Similarly, comparing the expression pattern of MUC4 with other proteins like E-cadherin or other mucins will strengthen the study and may potentiate the possible use of MUC4 as a diagnostic and prognostic marker for gastric adenocarcinomas." (PMID 18781152, 2008). "Similar findings showing the overexpression of MUC4 in gastric adenocarcinoma has been reported earlier." (PMID 18781152, 2008). "Immunohistochemical analysis using tissue microarray (TMA) showed a significant difference in MUC4 expression between normal adjacent (n=45) and gastric adenocarcinoma (n=83; P<0.001)." (PMID 18781152, 2008). "To date, no extensive study has been done to check the expression and functional significance of MUC4 in different types of gastric adenocarcinomas." (PMID 18781152, 2008). "Using immunoblot assay, MUC4 expression was checked in three different types of gastric adenocarcinoma cell lines (AGS, MKN45 and KATOIII)." (PMID 18781152, 2008). "In conclusion, our results showed that MUC4 is overexpressed in gastric adenocarcinoma tissues, and that it has a role in promoting aggressive properties in poorly differentiated gastric non-SRCC cells through the activation of the ErbB2 oncoprotein." (PMID 18781152, 2008). "Realizing the importance of MUC4 in different malignancies, we prompted to investigate the expression pattern of MUC4 in different gastric adenocarcinomas." (PMID 18781152, 2008). "Here, we report the expression profile of MUC4 in gastric adenocarcinomas and its function in poorly differentiated gastric non-signet ring cell carcinoma (non-SRCC) type cells." (PMID 18781152, 2008).
lung squamous cell carcinoma (6 papers, 2014 to 2022). "We evaluated 65 epithelioid mesotheliomas, 60 adenocarcinomas, and 57 squamous cell carcinomas of the lung for MUC4 expression by immunohistochemistry and compared with the previously known immunohistochemical markers." (PMID 29317712, 2018).
metastatic tumors (6 papers, 2009 to 2025). "Among the selected candidates, MUC4 was significantly up-regulated in both primary and metastatic samples of fast-progressing patients, whereas HTRA2 and RAB25 were significantly elevated only in primary samples and EPCAM only in metastatic tumors of the fast-progressing group." (PMID 36527824, 2023).
ovarian tumors (6 papers, 2008 to 2025). "Previously, our study has revealed an aberrant expression of MUC4 mucin in > 90% of different histological subtypes and grades of ovarian tumors with very low or undetectable expression in the normal ovary." (PMID 21521521, 2011). "MUC1 and MUC4 are also known to be overexpressed in ovarian tumors." (PMID 20034397, 2009). "The much higher expression of mucins (MUC1, MUC4, MUC5AC, MUC13 and MUC16) in ovarian tumors compared to the surrounding normal tissues can be exploited for the purpose of radioimmunodiagnosis (RID) and radioimmunotherapy (RIT)." (PMID 20034397, 2009). "Various studies have shown the overexpression of MUC1, MUC2, MUC3, MUC4, MUC5AC and MUC16 in a variety of ovarian tumors." (PMID 20034397, 2009). "Different studies on the expression of mucins in ovarian tumors have shown overexpression of MUC1, MUC2, MUC3, MUC4, MUC5AC and MUC16 or CA125." (PMID 20034397, 2009). "Our recent and some previous studies showed the overexpression of MUC4 in a majority of early stage ovarian tumors and a combined panel of MUC1, MUC4 and MUC16 dramatically increased the sensitivity of MUC16 staining test." (PMID 20034397, 2009). "While the testicular tumors were not tested for ALK and MUC4, recent reports of histologically similar ovarian tumors confirmed MUC4 expression." (PMID 39031200, 2024). "Previous studies from our laboratory have revealed an aberrant expression of the MUC4 in more than 90% of ovarian tumours, whereas a very low to no expression was detected in the normal ovaries." (PMID 18665193, 2008).
sarcoma (6 papers, 2018 to 2025). A usually aggressive malignant neoplasm of the soft tissue or bone. "In conclusion, the results of our research emphasize the diagnostic importance of MUC4 in these particular sarcoma subtypes." (PMID 38156143, 2023). "The study provides crucial insights into the diagnostic significance of MUC4, particularly in the context of specific sarcoma subtypes." (PMID 38156143, 2023). "However, there are still many unsolved problems regarding the sensitivity and specificity of MUC4 as a diagnostic marker across a broad spectrum of sarcoma subtypes in the larger context of sarcoma pathology." (PMID 38156143, 2023). "The present study examines the diagnostic capacities of mucin-4 (MUC4), a transmembrane mucin, in identifying different types of sarcomas and broadens its evaluation to include a wide range of sarcomas." (PMID 38156143, 2023). "In conclusion, this study adds to our understanding of soft tissue sarcomas by emphasizing the crucial role of MUC4 in certain sarcoma subtypes while acknowledging the complex variety of the sarcoma landscape." (PMID 38156143, 2023). "In the findings of the current study, SEF and LGFMS exhibit strong MUC4 expression, other sarcoma types including fibrosarcoma, liposarcoma, MPNST, myxofibrosarcoma, and leiomyosarcoma showed no MUC4 expression." (PMID 38156143, 2023). "As a result, the effect of gender and age on MUC4 expression in these sarcomas was studied in the current study, but the findings supported the previously published literature." (PMID 38156143, 2023). "Immunohistochemical (IHC) examination of tissue samples from various sarcomas was performed using a mouse anti-MUC4 monoclonal antibody." (PMID 38156143, 2023). "However, it is essential to emphasize that the study's primary focus on MUC4 expression in specific sarcomas, including SEF and LGFS, adds depth to our understanding of sarcoma markers." (PMID 38156143, 2023). "The findings show that there is no considerable MUC4 expression in other sarcoma types, emphasizing the importance of broad diagnostic panels." (PMID 38156143, 2023). "Our explorations of MUC4 activity in the context of sarcoma diagnosis go beyond SEF and LGFMS." (PMID 38156143, 2023). "Similarly, MUC4 was upregulated in one dataset while it was downregulated in one dataset in sarcoma." (PMID 34336844, 2021). "Secondly, a SEF lacking MUC4 expression that could be a more aggressive form of SEF as MUC4 expression had been reported to be associated with epithelial glandular differentiation in other sarcomas." (PMID 30187231, 2018). "Results showed that the tumor was in close proximity to the SEF group, admixed together with the other YAP1::KMT2A MUC4 negative SEF sarcomas." (PMID 40879254, 2025). "This study investigates the intricate intricacies of sarcoma pathology, examining the potential diagnostics sensitivity of MUC4 in not just these two particular subtypes but also in a wide range of sarcomas." (PMID 38156143, 2023). "A small subset of MUC4-negative SEF-like sarcomas harbors recurrent YAP1::KMT2A fusions." (PMID 39031200, 2024). "Importantly, the absence of considerable MUC4 expression in liposarcoma distinguishes it from other types of sarcomas." (PMID 38156143, 2023). "Furthermore, this study investigates the influence of age and gender on MUC4 expression in a range of sarcomas, which was typically understudied in the literature and found no relation with expression of MUC4." (PMID 38156143, 2023).